CGA (glycoprotein hormones, alpha polypeptide)
Diseases named in the same sentence as CGA in open-access papers (continued):
Sharing a sentence is not in itself a finding about the gene and the disease.
cancer (continued). "The biopsy was performed, indicating poorly differentiated carcinoma, and the subsequent immunohistochemistry results showed PCK (+), EMA (±), CDX2 (−), CgA (−), Syn (−), CD20 (−), CD3 (−), Ki67 (+, 50%), CK8/18 (+), P63 (+), CK5/6 (+), CK7 (−), and EBER1/2‐ISH (+)." (PMID 37732493, 2023). "Moreover, we found two key TFs (EPO, ARID3A), four key PRSGs (CACNA1E, LINC01356, CGA and SSX3) and five key hallmarks of cancer gene sets (DNA repair, myc targets, E2F targets, mTORC1 signaling and unfolded protein response) in the regulatory network." (PMID 33816287, 2021). "Within the CgA+ group, right-sided tumors were more frequent (18.5% vs. 53.3%), no stage I cancer was found, and patients of this group were in worse general condition." (PMID 33383764, 2020). "The results of this study demonstrate that CgA is a valuable marker for histological diagnosis of NEN of the colon and rectum, but a very poor plasma marker for follow-up patients suffering from this type of cancer." (PMID 29232390, 2017). "Similarly, Angulo and his co-workers did not observe a correlation with baseline CgA levels (tissular) and cancer-specific survival in 45 men with advanced PC." (PMID 36527470, 2023). "While physiologic concentrations inhibit both spontaneous and VEGF- and FGF-2-induced angiogenesis, the anti-angiogenic effect is lost at supraphysiologic CgA concentrations, suggesting that high CgA levels, as occur in NE and some non-NE cancers, might reduce the anti-angiogenic effect." (PMID 25785244, 2015). "Firstly, we compared the expression of CgA and SYP between malignant tumors and corresponding non-cancerous tissues." (PMID 36899368, 2023). "PTH, GCM2, SYN, CgA, GATA3, and CAM5.2 are always positive in cancer cells, while TTF1, PAX8, CAL, and TG are always negative." (PMID 38019325, 2023). "By immunohistochemistry, SCOOHT showed the expression of CD56, CgA, Syn, CK (Pan), EMA and other cancer markers, but SDUS is not expressed." (PMID 37194064, 2023). "SUDS did not express CK, CD56, CgA, Syn, EMA and other cancer markers, but expressed Vimintin." (PMID 37194064, 2023).
adenocarcinoma (13 papers, 2004 to 2024). A common cancer characterized by the presence of malignant glandular cells. "When considering all 29 adenocarcinomas, there was a strong association between CgA protein and synaptophysin protein (r = 0.7, p < 0.01), and CgA protein and CgA mRNA (r = 0.6, p < 0.01))." (PMID 28980157, 2018). "CgA mRNA was observed in 20 of 29 (69%) adenocarcinomas, where six of ten (60%) intestinal type, 11 of 15 (73%) diffuse type, and three of four (75%) mixed/indeterminate type were positive." (PMID 28980157, 2018). "LNCaP-NK1R and 22Rv1-NK1R demonstrated significant expression of NE marker CgA and ENO2 as well as the NE-related gene while the level of adenocarcinoma marker AR and PSA reduced." (PMID 37385990, 2023). "Of the 29 adenocarcinomas examined, 12 tumors expressed CCKBR mRNA, and 11 of these tumors co-expressed CgA mRNA." (PMID 28980157, 2018). "Co-expression of CCKBR mRNA and CgA mRNA and CCKBR mRNA and HDC mRNA was frequently observed, which makes sense as the NENs and even some cases of adenocarcinomas of the diffuse type are thought to originate from ECL cells." (PMID 28980157, 2018). "One HAC patient had specific staining for Cromogranin A (CgA) and CD56, which were focally positive in both adenocarcinoma and hepatoid areas, illustrating neuroendocrine carcinomatous features, while synaptophysin (SYN) was negative." (PMID 24669215, 2014). "Recently, mixed forms between adenocarcinoma and neuroendocrine prostate cancer (NEPC) have emerged that are characterized by persistent androgen receptor (AR)-signalling and elevated chromogranin A (CgA) levels." (PMID 30337589, 2018). "Of note, immunostaining showed that all seven tumors were adenocarcinomas before the treatment, evidenced by staining positive for both AR and PSA, and staining negative for SYP, CD56, and CgA, whereas most of them became AR‐ and PSA‐negative, and SYP‐, CD56‐, and CgA‐positive after ADT." (PMID 33009820, 2021). "Immunohistochemically, the adenocarcinoma cells were positive for CEA but negative for chromogranin A (CgA) and synaptophysin (Syn), while the non-adenocarcinoma cells were positive for the expression of CgA and Syn but negative for CEA." (PMID 27848241, 2016).
cardiovascular diseases (11 papers, 2019 to 2025). "In the future, we may further explore whether plasma CgA levels can be used to determine the future risk of cardiovascular disease in these populations." (PMID 32515855, 2020). "Several studies have addressed the role of circulating CgA as a biomarker in patients with cardiovascular diseases using CgA‐ELISA systems that were unable to discriminate between the full‐length CgA and its fragments." (PMID 31588572, 2019). "Therefore, we believe that the activation of sympathochromaffin/CgA axis may play an important role in the development of cardiovascular disease in anxious and depressed individuals." (PMID 32515855, 2020). "Furthermore, we thought that the activation of sympathochromaffin/CgA axis may play an important role in the development of cardiovascular disease in anxious and depressed people." (PMID 32515855, 2020). "Univariate analyses found a correlation between baseline CgA levels with the two coprimary outcome measures in GISSI‐HF: mortality and mortality of hospitalization for cardiovascular disease during follow‐up." (PMID 31588572, 2019).
heart disease (8 papers, 2012 to 2024). "CgA has also been detected in endomyocardial biopsy material in people with heart disease, as well as in normal heart tissues where a decrease in CST concentration was observed with age." (PMID 37445245, 2023). "Plasma CgA concentrations have been shown to increase with the advancement of various human heart diseases." (PMID 37445245, 2023). "However, the predictive power of CgA in NEN is limited by its susceptibility to interference by drugs (e.g., proton pump inhibitors), impaired kidney function, heart diseases, or rheumatoid diseases." (PMID 34064565, 2021). "Increased plasma concentrations of CgA have been shown in people with heart disease." (PMID 32758260, 2020). "CgA has been demonstrated to provide incremental prognostic information to established indices of risk, including BNP, in several cohorts of patients with cardiac disease, while CgB has been proposed as a marker associated with cardiomyocyte calcium handling." (PMID 22655045, 2012). "Plasma concentrations of CgA or derived peptides have not been investigated in dogs with heart disease." (PMID 32758260, 2020).
infection (5 papers, 2015 to 2025). The state of being infected such as from the introduction of a foreign agent such as serum, vaccine, antigenic substance or organism. "A prognostic value of CgA has been found in humans that are critically ill or that have SIRS associated with infection." (PMID 25636335, 2015). "Moreover, increased CgA concentration has prognostic value in human patients suffering from stress, critical illness or infection associated with SIRS." (PMID 25636335, 2015). "Because of those properties, short, recombinant CgA peptides are studied as possible therapeutic agents during certain, difficult-to-treat, antibiotic-resistant infections." (PMID 40370467, 2025). "The antimicrobial and antifungal effects are achieved through CgA cleavage products, which are released by intestinal wall cells, certain immune cells – neutrophils, at the site of infection/injury, as well as systematically, e.g., by the adrenal medulla." (PMID 40370467, 2025). "This review aims to summarize the not fully understood role of CgA and its derivatives in inflammation, autoimmunity, and infections." (PMID 40370467, 2025). "If confirmed prospectively, plasma CST will reliably help in predicting in-hospital mortality, whereas CgA will facilitate the detection of patients prone to care-related infections." (PMID 36248786, 2022). "Possibly there is a system for downregulation of CgA in response to infection, at least in some animal species." (PMID 25636335, 2015). "For more knowledge and understanding of mechanisms and roles of CgA in dogs with infection, further studies are necessary." (PMID 25636335, 2015). "Finally, in the severest group of COVID+ICU+ patients, with a cut-off value of 12.75 ng/mL, admission CgA predicts the occurrence of care-related infection with a sensitivity of 87.5% [67.6-97.3] and a specificity of 48,0% (AUC=69.42 [54.30; 84.54], p=0.015)." (PMID 36248786, 2022). "Our study confirms the reliability of CgA in predicting morbidity issues (ie: care-related infections) but not mortality in line with data in trauma patients." (PMID 36248786, 2022). "So far, concentrations of CgA have not been investigated in dogs with infection or before and after surgery." (PMID 25636335, 2015).
bacterial infection (4 papers, 2013 to 2022). "The more active antimicrobial CgA-derived peptides are elective candidates for medical implant functionalization in order to prevent fungal or bacterial infections after implantation." (PMID 36090980, 2022). "The higher serum and salivary cortisol and higher serum CgA concentrations demonstrated in the PDS+ sows may reflect differences in stress level in the two groups, but could also be related to inflammation caused for example by a bacterial infection." (PMID 30404636, 2018). "CgA has not yet been studied in dogs with bacterial infection." (PMID 25636335, 2015).
renal disease (4 papers, 2019 to 2025). "CgA, while widely used, has limitations including variable sensitivity (60–90%) and specificity (60–85%) due to renal disease or drug interference." (PMID 40624075, 2025). "Additionally, CgA is never a first-line diagnostic test and should not be considered a viable tool for screening as the specificity of the CgA assay decreases up to 50% in populations with concomitant conditions, such as GI or renal disorders." (PMID 31382663, 2019).
endocrine disease (2 papers, 2021 to 2025). "Based on the link between CgA and its cleavage products to various endocrine diseases and their presence in pancreatic islets, we aimed to investigate how CgA, CST, and PST may influence pancreatic islet endocrine function, islet morphology and the islet microenvironment." (PMID 41298823, 2025).
gastrointestinal disorders (2 papers, 2021 to 2022). "In addition, there could be a role of CgA in the gastrointestinal disorders associated with PDS, since in the human gastrointestinal tract, CgA is released from enterochromaffin cells and neurons of the submucosal and myenteric ganglia, and may modulate colonic motility in response to inflammation." (PMID 35227252, 2022).
lung (2 papers, 2022 to 2023). "In a 2020 paper, Matar and co-researchers showed that CgA is not a clinically useful biomarker in diagnosing lung NENs." (PMID 37444393, 2023).
metabolic disease (2 papers, 2018 to 2025). A congenital disorder (due to inherited enzyme abnormality) or acquired (due to failure of a metabolically important organ) disorder resulting from an abnormal metabolic process. "The involvement of CgA in metabolic regulation has prompted investigations into its role in metabolic diseases." (PMID 41480370, 2025). "Thereby, the generation of CgA cleavage products might be regulated by sugar levels and this might play a role in progression of metabolic diseases, as for instance the increased blood glucose levels in T2DM might promote glycosylation of CgA." (PMID 30337922, 2018).
psychiatric disorder (1 paper, 2021). A disorder characterized by behavioral and/or psychological abnormalities, often accompanied by physical symptoms. "None of these patients were diagnosed with other neurological or psychiatric disorders that could affect the CSF CgA level." (PMID 33499181, 2021).
CGA also shares sentences with these, for which no sentence is quoted: neurodegenerative disease (5 papers); rheumatoid arthritis (5); coronary heart disease (4); myocardial infarction (4); pancreatic cancer (4); pituitary adenomas (4); liver cirrhosis (3); ulcerative colitis (3); chronic gastritis (2); Cirrhosis (2); essential hypertension (2); hyperthyroidism (2); metabolic syndrome (2); pancreatitis (2); thyroid cancer (2); ZIKV infection (2); acid reflux (1); age (1); atopic dermatitis (1); autoimmune gastritis (1); basaloid carcinoma (1); brain disorder (1); cardia (1); cardiac arrest (1); cerebrovascular disease (1); cholelithiasis (1); choriocarcinoma (1); chromaffin tumors (1); chronic obstructive pulmonary disease (1); chronic periodontitis (1).
A further 71 diseases each share a sentence with CGA in 1 paper.